BRCA1 (BRCA1 DNA repair associated)
Diseases named in the same sentence as BRCA1 in open-access papers (continued):
Sharing a sentence is not in itself a finding about the gene and the disease.
tumor (continued). "We found that younger age at diagnosis as well as lymphocytic infiltration and expression of the basal cytokeratin 5/6 in the tumor significantly increased the likelihood that a TNBC was associated with a BRCA1 mutation." (PMID 28721372, 2016). "BRCA1 is a tumour suppressor implicated in DNA repair, transcription, chromatin remodelling and cell survival." (PMID 27845331, 2016). "An elegant study recently reported that loss of tumour suppressors BRCA1 or BRCA2 increases R-loop levels, because these proteins act to prevent R-loop formation." (PMID 27725641, 2016). "A tumor sub-type independent increase in numbers of ALDH1+ cells was observed in BRCA1-mutated cell lines MDA-MB-436 (8.4 ± 0.2 %) and HCC1937 (6.9 ± 0.5 %) when compared to cells possessing a wild type BRCA1." (PMID 27229859, 2016). "For example, tumor-specific somatic inactivation of BRCA1 is the frequent cause of BRCA-ness phenotype." (PMID 27555886, 2016). "Although the mutation frequency observed is high, our sample size is relatively small and further studies are warranted to confirm the association of BRCA1/BRCA2 mutations with this rare neoplasia." (PMID 27532258, 2016). "There were 27 unique BRCA1 variants within these 37 individuals, five of which had at least two independent tumor samples from different analyzed individuals, and the logistic regression model resulted in probabilities of pathogenicity for each sample." (PMID 26727311, 2015). "Pre-clinical work demonstrated that these inhibitors cause synthetic lethality in tumour cells with BRCA1 or BRCA2 gene defects, an observation that has also been confirmed in clinical trials." (PMID 25883215, 2015). "On the basis of our systematic and evidence-based analysis of all studies published to date, we conclude that there is only moderate evidence for a worse recurrence-free survival for BRCA1 mutation carriers, unadjusted for tumour characteristics." (PMID 25816289, 2015). "Despite this information, it has still remained unclear why mutation in a single copy of BRCA1 leads to rapid tumour onset in such a tissue- and cell-type-specific manner." (PMID 26106036, 2015). "With one exception, that being a tumour sample harbouring a BRCA1:C4446T mutation, all identified mutations were detected in the germline." (PMID 25884701, 2015). "We previously observed that tumor DNA methylation can differentiate BRCA1-mutated from BRCA1-wild type tumors." (PMID 26727311, 2015). "Similar results confirmed the association of low BECN1 expression with ER-negative tumor subtypes when the analyses were confined to tumors with BRCA1 deletions." (PMID 25825707, 2015). "Terminal mutations of the BRCA1 or BRCA2 genein tumor cells lead to defects in the homologous DNA recombination system whosenormal activity involves both BRCA proteins." (PMID 26483957, 2015). "The protein stained in the cytosol was considered to be a mutated form of BRCA1 and loss of nuclear BRCA1 expression is associated with a highly proliferative tumor phenotype." (PMID 25774336, 2015). "Some BRCA1 variants, such as splicing variants, can be expressed in the tumor but can lose their interaction with their partners." (PMID 26490435, 2015). "Rather, the idea of ‘obligatory haploinsufficiency'30 is better suited to describe BRCA1-associated tumour progression, since decreased levels of BRCA1 are sufficient to produce abnormal cellular phenotypes." (PMID 26106036, 2015). "It has been reported that tumor cells with BRCA1/2 mutation, since their deficiency in homologous recombination, are markedly sensitized to the PARP inhibition, resulting in chromosomal instability and consequent apoptosis." (PMID 25366421, 2015). "Following clinical trials also provided proof of concept of olaparib single-agent activity of PARP inhibition in patients with tumours that have genetic loss of function of BRCA1-associated or BRCA2-associated DNA repair." (PMID 26610585, 2015).
tumor (continued). "In an attempt to clarify the role played by a mutated BRCA1 allele in the GBM development, we assessed BRCA1 mRNA and protein expression in the two tumour types for each patient." (PMID 25880076, 2015). "3/BRCA1 mutation does initiate the tumor and the apparition of mutations triggers a cascade of reparatory mechanisms." (PMID 26426992, 2015). "Basal keratins are expressed by both sporadic basal-like tumours and tumours with BRCA1 mutations, and both groups cluster together by gene expression profiling." (PMID 26387133, 2015). "BARD1 is a major binding protein of the breast cancer predisposition gene product BRCA1 and a tumor suppressor in its own right." (PMID 26415510, 2015). "The tumor-associated BRCA1 gene is knownto play an important role in the repair of double-strand breaks through the HRmechanism." (PMID 26483957, 2015). "Combining radiation therapy with PARP inhibitors offers promise, since the inhibitors would lead to formation of double strand breaks from the single-strand breaks generated by the radiotherapy in tumor tissue with BRCA1/BRCA2 mutations." (PMID 25606064, 2015). "At the tumor level the mutation in BRCA1 was also detected, however, at the lower allelic proportion compared to the germline (Figure 4B2)." (PMID 26426992, 2015). "Deficient HR can be deduced from identified inactivating mutations of already known genes (such as BRCA1 or RAD51) in tumor biopsies; however, the major challenge is represented by prediction of the drug resistance development." (PMID 26295265, 2015). "Breast cancer susceptibility gene 1 (BRCA1) was the first tumor suppressor gene identified in breast and ovarian cancer." (PMID 26490435, 2015). "Hypermethylation was associated with advanced tumor grade for BRCA1 (P = 0.003), CDH1 (P = 0.002), HSPA2 (P = 0.009), RASSF1A (P = 0.017), and THBS1 (P = 0.000), while methylated GDF15 (P = 0.002) promoter was associated with low tumor grade." (PMID 25613404, 2015). "There was trace evidence for the normal allele in the sequencing chromatogram from the tumour sample containing the BRCA1 mutation." (PMID 25884701, 2015). "More importantly, the effect of mutations within different genes and pathways seem to complement each other and result in a specific signature characteristic for BRCA1/2-deficient tumours." (PMID 26632267, 2015). "This suggests the existence of common targetable miRNA regulated pathways driving BRCA1/2-associated breast carcinogenesis." (PMID 26378051, 2015). "The BRCA1 tumour suppressor gene encodes for a multifunctional protein that has been implicated in many normal cellular functions such as DNA repair, transcriptional regulation, cell-cycle checkpoint control, and ubiquitination." (PMID 26061043, 2015). "The absence or weak staining of BRCA1 which was considered as BRCA1 mutation, was also significantly associated with tumor type (P = 0.048)." (PMID 26490766, 2015). "What is interesting about the presented case is the existence of a LOH in BRCA1 locus associated with the loss of the mutated allele in the tumor." (PMID 26426992, 2015). "Taken together, these data suggest that inactivating BRCA1-IRIS suppresses the tumor-initiating phenotype, implicated in aggressiveness and recurrence of TNBC cells." (PMID 25583261, 2015). "A number of studies reported similar data with regard to the prevailing node-negativity in BRCA1 mutation carriers, even in patients with large tumor size." (PMID 24348864, 2014). "BRCA1 expression has been previously associated with several tumor, such as breast, esophageal, gastric, ovarian, bladder and non-small cell lung tumors." (PMID 25594033, 2014).
tumor (continued). "The breast cancer susceptibility gene 1 (BRCA1) has been well established as a tumor suppressor and functions primarily by maintaining genome integrity." (PMID 24704793, 2014). "Combined treatment with rapamycin and PARP inhibitor effectively suppresses BRCA1-deficient tumor growth in mice." (PMID 24831086, 2014). "Collectively, our data suggest that CD338 expression is specific to the tumor-initiating luminal progenitor subpopulation of BRCA1-mutated cells and is a novel antigen with which to sort this subpopulation." (PMID 25216750, 2014). "These were: histological tumor type and grade, FIGO (International Federation of Gynecologists and Obstetricians) clinical stage, the volume of residual tumor left after surgery, and a germline BRCA1 gene mutation." (PMID 24478986, 2014). "Treatment with olaparib resulted in modest reduction of tumor growth in the Brca1-deficient 30200 tumor model and in significant reduction in model 39877 (p<0.01)." (PMID 24748377, 2014). "For TN tumor phenotype, the original LR for BRCA1 mutation status was 3.73, whereas the median of the five replicates was 3.76." (PMID 25857409, 2014). "In general, decrease in cell proliferation and increase in DNA damage correlated with tumor growth inhibition observed in Brca1-deficient lines." (PMID 24748377, 2014). "BRCA1 is a tumor suppressor gene located on chromosome 17q21 and encodes a multi-domain protein of 1863 amino acids which is involved in important cellular functions such as in DNA repair, transcription and cell cycle control through the DNA damage response." (PMID 24695549, 2014). "BRCA1 is a classic tumor suppressor gene and the loss of the wild-type allele [loss of heterozygosity (LOH)] is required for tumorigenesis in germline mutation carriers." (PMID 25177489, 2014). "Preclinical and clinical studies have reported that BRCA1 level of tumor is associated with cisplatin and taxanes chemosensitivity." (PMID 25496700, 2014). "We further performed regression analysis of Luminal A cases alone, evaluating the effect of patient age, menopausal status, disease stage, tumor stage and grade on the BRCA1-3’UTR-variant status." (PMID 24915755, 2014). "Loss of PI3K resulted in reduced BRCA1 expression both in cell line models and in patient-derived tumor xenografts." (PMID 24624361, 2014). "An association between miR-146a phenotype and tumor age-of-onset in BRCA1/2-negative familial BC cases has been reported." (PMID 25006670, 2014). "A BRCA1 loss of heterozygosity (LOH) event is a consistent characteristic of fully developed BRCA1-linked tumour cells." (PMID 25400221, 2014). "Loss or decrease of these PTEN or BRCA1 function, by either mutation or reduced expression, has a role in various tumor developments." (PMID 25426449, 2014). "In some cases, normal tissue shows LOH of the wild type BRCA1 allele, and tumor tissue shows loss of the mutant allele." (PMID 24950059, 2014). "We tested the effects of rapamycin and olaparib on Brca1-deficient tumors in mice and found that olaparib significantly inhibited S6−/− tumor growth." (PMID 24831086, 2014). "PARP inhibitors have shown remarkable sensitivity in BRCA1/2-deficient tumour models in vitro as well as in clinical trials involving carriers of BRCA1/2 germ line mutations." (PMID 24927325, 2014). "The present study indicated that BRCA1 methylation was significantly associated with the tumor location." (PMID 24944674, 2014). "Short term treatments (2–3 weeks) of Brca1-deficient tumors resulted in significant reduction of tumor volumes compared to vehicle treated mice, corresponding to the observed decreased proliferation and increased DNA damage." (PMID 24748377, 2014). "BRCA1-mutated tumor cells have a defective homologous-recombination repair pathway that predisposes a high sensitivity to DNA-damaging agents." (PMID 24348864, 2014). "CDDO-Me significantly delayed tumor development in the BRCA1-mutated mice by an average of 5.2 weeks." (PMID 24552536, 2014).
tumor (continued). "Reduced sensitivity of mouse Brca1-wild type tumors to platinum treatment cannot be attributed to slower tumor growth, since growth kinetics are similar between Brca1-deficient and -wild type tumors subsequent to establishment and prior to treatment." (PMID 24748377, 2014). "Sequencing of matched tumor and normal DNA samples determined that 75% of BRCA1/2 mutant tumors carried a germline BRCA1/2 mutation." (PMID 25475740, 2014). "What is apparent is that BRCA1-associated tumours in males appear to be more similar to the tumours seen in post-menopausal female BRCA1 carriers, with an absence of tumours arising in young patients and an absence of an association with basal cell phenotype." (PMID 23971979, 2013). "BRCA1 inactivation is usually predisposed to early-onset tumors, with a distinct phenotype characterized by high tumor grade, aneuploidy, high proliferation rate, and ER-negativity." (PMID 23555992, 2013). "Mean percent of tumor cells that showed the reaction for selected proteins as well as the intensity of immunostaining for all analyzed proteins seems to be lower in BRCA1 mutation carriers." (PMID 23553196, 2013). "Next, we performed hierarchical clustering including the additional 10 tumors from patients carrying UVs in the BRCA1/2 genes and the TP-53 associated tumor." (PMID 23469205, 2013). "In our series, BRCA1 promoter hypermethylation was found in 18 tumours and was significantly associated with a more aggressive clinico-biological profile and with triple negativity." (PMID 24191908, 2013). "On the other hand, an association between TOX3 overexpression in tumours and lower BRCA1 expression and tumour aggressiveness has been reported recently." (PMID 24069272, 2013). "We performed exome sequencing on the blood, primary tumor, omental metastasis and recurrence following therapy with carboplatin and paclitaxel, from a patient carrying a BRCA1 S1841R mutation." (PMID 23522120, 2013). "The low numbers of MBCs in BRCA1 mutation carriers in our study reflects the paucity of these tumours in this particular cohort, and in BRCA1 carriers in general." (PMID 23971979, 2013). "The CtIP protein interacts with BRCA1 protein, and the BRCA1-CtIP complex is thought to mediate 5’ end resection of DSBs, which is abrogated by three independent tumor-associated mutations in the BRCT domain of BRCA1." (PMID 24970157, 2013). "By evaluating the frequency of tumor subtypes as a function of the mutation status of individual genes, our data revealed that 6 out of 7 (85.7%) BRCA1 mutation-carriers developed HR(−) tumors; among them, 5 were TN (71.4%)." (PMID 23469205, 2013). "Of particular interest, TNBCs include a subset of neoplasms with a basal-like subtype that are often associated with BRCA1 mutations and are characterized by expression of genes usually found in basal or myoepithelial cells of the normal human breast." (PMID 24004841, 2013). "Only 3 studies have investigated the classification potential of gene-expression tumor profiles in relation to BRCA1/2 mutation status." (PMID 23704984, 2013). "Loss of BRCA1 nuclear expression correlates with high tumour grade (p < 0.025) and ER-negative tumours." (PMID 24191908, 2013). "The encoded protein combines with other tumour suppressors, DNA damage sensors, and signal transducers to form a large multisubunit protein complex, known as the BRCA1-associated genome surveillance complex." (PMID 23586058, 2013). "HR-deficient tumours, such as those with BRCA1 or 2 hypomorphic mutations, are very susceptible to poly(ADP ribose) polymerase (PARP) inhibitors." (PMID 23505385, 2013). "It was shown that some LGRs in BRCA1 gene including exons 17 and 20 deletions were associated with previously defined tumor morphology." (PMID 24312913, 2013).
tumor (continued). "The spectrum of tumours in families segregating BRCA1 and BRCA2 mutations includes pancreatic, prostate, colon and skin cancers." (PMID 24025454, 2013). "In our study, we also found diffuse, and irregular BRCA1 protein staining with the K-18 antibody in the frozen section tumor tissue from a patient, with a BRCA1 mutation (185delAG), which is difficult to explain." (PMID 23855721, 2013). "A clear illustration of the antagonistic relationship between 53BP1 and BRCA1 is seen in mouse models, where the embryonic lethality, tumor predisposition, and HR defect of Brca1-deficient mice can be rescued by deleting 53BP1." (PMID 23333305, 2013). "BRCA1 encodes a nuclear phosphoprotein, which acts as a tumour suppressor gene through maintaining genomic stability." (PMID 23586058, 2013). "For instance, activation of SIRT1 by resveratrol was shown to limit cell growth and reduce tumour formation in BRCA1-deficient tumour cells as well asTrp53+/−;Sirt1+/− mice." (PMID 24223900, 2013). "Multiple germline mutations that disrupt Bach1 enzyme activity or BRCA1 association have been identified in breast cancer indicating Bach1 is a tumor suppressor." (PMID 22369660, 2012). "This suggests a common tumourigenic pathway of the BRCA1 and basal-like subtypes; however, the biological mechanisms associated with increased frequency of chromosomal changes in these tumour types are currently poorly understood." (PMID 22434526, 2012). "The breast cancer susceptibility gene (BRCA1), a tumor suppressor gene, encoded a factor inhibiting cell growth." (PMID 23276146, 2012). "It is likely additional BRCT associated complexes exist carrying additional roles of BRCA1 in a number of diverse cellular processes in maintaining genome stability and tumor suppression." (PMID 22369660, 2012). "A number of phenotypical and molecular features are shared by basal-like breast cancer and tumours arising in BRCA1 germline mutation carriers, including high grade and a high number of chromosome copy number changes." (PMID 22434526, 2012). "Clearly, mutations of BRCA1 NLSs causing cytosolic expression of BRCA1 would decrease the tumor suppressor activity of BRCA1 due to the loss of BRCA1's DNA repair activity and subsequent increase in unrepaired mutations and chromosomal abnormalities." (PMID 22737296, 2012). "The high rate of mutations in specific domains of BRCA1 suggests that these domains are critical for its tumor suppressor activity." (PMID 22737296, 2012). "BRCA1 is a classic tumor suppressor gene in that loss of the wild-type allele (loss of heterozygosity, LOH) is required for tumorigenesis in germline mutation carriers." (PMID 22347400, 2012). "Of these subtypes, the basal-like tumour subtype, which is common in BRCA1 mutation carriers, is characterised by a high number of chromosomal copy number changes." (PMID 22434526, 2012). "Among new therapies that are under investigation, the most important one is PARP inhibition, which induces synthetic lethality in tumour cells deficient in homology-directed DNA double-strand break repair such as cells mutated in BRCA1 or BRCA2." (PMID 23110154, 2012). "The distribution of grade has been found to vary between ER-positive and ER-negative tumours in both BRCA1 and BRCA2 mutation carriers (Mavaddat N, Antoniou AC, personal communication, manuscript in preparation)." (PMID 22053997, 2011).